PIK3CA (phosphatidylinositol-4,5-bisphosphate 3-kinase catalytic subunit alpha)
Diseases named in the same sentence as PIK3CA in open-access papers (continued):
Sharing a sentence is not in itself a finding about the gene and the disease.
glioma (continued). "The interplay between both neuronal hyperexcitability and glioma progression has been demonstrated for certain PI3KCA (phosphatidylinositol-4,5-bisphosphate 3-kinase catalytic subunit alpha) variant tumors." (PMID 36357661, 2022). "c.1633G>A in PIK3CA is reported to be associated with different tumors, including glioma (COSM763) and in megalencephaly-capillary malformation (CM126692)." (PMID 35456430, 2022). "Mutations in the PIK3R1gene have been shown to promote the growth and formation of gliomas, while PIK3CA missense mutations have been shown to promote GBM pathogenesis." (PMID 32041307, 2020). "On the other hand, samples bearing PIK3CA mutations perturbing the N-terminal SH2 domain of regulatory subunits are associated with poorer prognosis in low grade glioma (p = 1.4e−3, q = 3.79e−2)." (PMID 27698488, 2016). "Losses and mutations of NF1 and PTEN, as well as amplification and mutation of PIK3CA were preferentially found in the RMPAhigh gliomas." (PMID 27385209, 2016). "The network topology analysis performed in this study revealed a set of central nodes associated to glioma malignancy, such as Map3k14, Mapk1, Actn4, Hspa5, Atf2, Rac1,E2f1, Shc1, Pik3ca, Akt1, Vim and Egr1." (PMID 26582089, 2015). "Moreover, we also discuss the therapeutic potential and challenges of targeting PIK3CA mutations in the context of glioma." (PMID 40508087, 2025). "Furthermore, the relationship between PTEN deficiency and PIK3CA mutations and how it affects alpelisib treatment response in glioma must be further explored." (PMID 40508087, 2025). "Current evidence suggests that PIK3CA mutations may represent early and constitutive events in glioma development, associated with worse glioblastoma prognoses, earlier recurrences, and widespread disease." (PMID 40508087, 2025). "For pediatric cancers, data from St Jude Children’s Research Hospital PeCan genomics data portal show that only 1 % of pediatric cancers have activating PIK3CA mutations, with pediatric high-grade gliomas being the only diagnosis with 10 % or higher PIK3CA mutation frequency." (PMID 39510293, 2024). "The alterations of CDKN2B, KMT5B, MAP2K1, PIK3CA, and chr9p were associated with hemorrhage, and this may be due to the fact that most of them affect glioma cell proliferation and invasion." (PMID 38877400, 2024). "PIK3CA gene also had a large percentage of patients with somatic variants in multiple cancer types such as bladder (21.0%), breast (39.8%), colorectal (17.5%), endometrial (42.3%), glioma (7.8%), lung (6.6%) and ovarian (12.4%)." (PMID 39277826, 2024). "Furthermore, our analysis revealed that NF1, PIK3R1 and PIK3CA are commonly mutated genes in H3F3A-mutant gliomas (24.6%, 17.7%, and 7.7%, respectively)." (PMID 37524847, 2023). "Mutations of PIK3CA lead to neuronal hyperactivity during formation of glioma." (PMID 36052751, 2022). "In addition, three of the diffuse midline gliomas and one of the hemispheric gliomas had mutation in PIK3CA, indicating a critical role of the PI3 kinase pathway in tumorigenesis." (PMID 34257334, 2021). "In contrast, grade II and III gliomas showing low expression levels of this mRNA were more frequently mutated in the PIK3CA gene, which may be plausibly linked to poor prognosis." (PMID 34771425, 2021).
glioma (continued). "Moreover, TERT promoter mutations coexist with PIK3CA mutations in 12% of anaplastic thyroid cancers, but only in 7.5% of gliomas." (PMID 29222734, 2018). "Importantly, a conditional mouse model in which the Pik3ca-H1047R mutation and Pten deletion are targeted to neural stem cells develops rapidly growing aggressive glioma-like tumors." (PMID 28556811, 2017). "Thus, the use of PIK3CA mutations as actionable targets in glioma should be explored further." (PMID 40508087, 2025). "At the time, everolimus and panobinostat were recommended for treating PIK3CA-mutated H3K27M-DMG, and temozolomide is a standard of care therapy for adult high-grade glioma." (PMID 40852486, 2025). "The team assessed the influence of KAT6A energy on the expression of PIK3CA in glioma cells, and the result indicated that it effectively inhibited the expression of PIK3CA and the activation of the PIEK/AKT signaling pathway." (PMID 39947253, 2025). "Apart from these, WB also identified despite knockdown of NCAPH, overexpression of PIK3CA decreased E-Ca expression along with increase in the Snail, vimentin, and N-Ca expression in glioma cells." (PMID 38587786, 2025). "In the Glioma/Glioblastoma cancer, 67% (16/24) of tumors exhibited one disease-related variant, of which 94% (15/16) were in IDH1 and 6% (1/16) were in PIK3CA." (PMID 38448823, 2024). "Furthermore, the cooccurrence of FGFR1 and PIK3CA hotspot mutations was observed in two tumors pathologically diagnosed as oligodendroglioma and ependymoma (P2233_109T, P7708_112T), and both were assigned to the methylation class low-grade glioma, rosette-forming glioneuronal tumors." (PMID 37221626, 2023). "Downregulation of NEDD4L increases PIK3CA expression, thereby promoting glioma cell proliferation by activating the PI3K/AKT pathway." (PMID 38027016, 2023). "The macrophages or glioma cells were transfected with overexpressing plasmid or shRNA to study the effects of miR‐10b‐5p/NEDD4L/PIK3CA on M2 macrophage polarization, and glioma cell proliferation, migration, and invasion in vitro and in vivo." (PMID 36052751, 2022). "miR‐10b‐5p delivered by hypoxic glioma‐derived EVs accelerated macrophages M2 polarization to promote the progression of glioma via NEDD4L/PIK3CA/PI3K/AKT axis." (PMID 36052751, 2022). "In summary, miR‐10b‐5p delivered by hypoxic glioma‐derived EVs accelerated macrophages M2 polarization to promote the progression of glioma via NEDD4L/PIK3CA/PI3K/AKT axis." (PMID 36052751, 2022). "RT‐qPCR and immunohistochemistry displayed that PIK3CA level was higher in brain tissues from patients with glioma than in non‐glioma samples." (PMID 36052751, 2022). "The frequency of mutations for PIK3CA, MUC16 and TTN was significantly higher in high risk glioma cases (TTN, 26% vs. 7%; MUC16, 16% vs. 8%; PIK3CA, 10% vs. 3%)." (PMID 33946049, 2021). "We found that elevated NEK8 expression in glioma is associated with various clinical and pathological parameters (WHO grade, histological type, IDH, EGFR, PIK3CA status and primary therapy outcome) and survival time." (PMID 34374193, 2021). "Gpc3-knockout glioma cells with PIK3CA C420R exhibited prolonged survival compared to wild-type Gpc3." (PMID 34944870, 2021). "In order to further verify the role of PIK3CA in the process of circ_0000020 promoting the development of glioma, siRNA against PIK3CA was transfected into U251 cell line with circ_0000020 overexpression." (PMID 33509213, 2021).
glioma (continued). "Among the selected genes, 15 (Araf, Braf, Kras, Ccnd1, Cdk6, Igf1r, Nras, Pik3ca, Pik3r1, Pdgfra, Pdgfrb, Pdgfb, Akt1, Akt2, and Mdm2) were related to glioma and leukemia." (PMID 31523185, 2019). "We found that glioma models harboring alterations in PIK3CA/PIK3R1 and PTEN were highly sensitive to the antitumor effects of DS." (PMID 28423515, 2017). "Despite the increased PIK3CA (encoding the PI3K catalytic subunit α) and AKT3 expression in IDH-mutant glioma, the overall AKT activities were statistically lower than those of IDH-wildtype, as indicated by the mean AKT phosphorylation at Ser-473 and Thr-308." (PMID 27852048, 2017). "The genomic alterations in EGFR, PDGFRA, NF1, PTEN and PIK3CA were nearly exclusively found in the RMPAhigh gliomas." (PMID 27385209, 2016). "Compared with the findings reported by TCGA in 2015 and Dono and colleagues, the observed PIK3CA mutation frequency in 1p/19q codeleted and IDH-mutant gliomas was lower in this cohort (10% versus 20% and 14%, respectively), likely due to the more limited sequencing strategy." (PMID 40508087, 2025). "Importantly, overexpression of PIK3CA in glioma cells rescued knockdown NCAPH mediated proliferation, migration, invasion, and EMT processes." (PMID 38587786, 2025). "They found that KAT6A enhanced PIK3CA expression in the gliomas model, further, it could activate PI3K/AKT signaling." (PMID 39947253, 2025). "Mutations in the IDH1/2 have been identified in gliomas, and IDH-mutant low-grade gliomas (LGGs) may develop malignant transformation after further genetic alterations, such as Myc, PTEN, KRAS, PIK3CA, and MET, are acquired." (PMID 37063420, 2023). "Moreover, in glioma cells, miR-10b-5p increases PIK3CA expression by downregulating NEDD4L expression, thereby promoting the proliferation, migration, and invasion of glioma cells by activating the PI3K-AKT pathway." (PMID 38027016, 2023). "In addition to the most common glioma mutations, others were detected as PPM1D mutation (3 out 10 tested samples), PIK3CA mutation (2/10 tested), BCOR mutation (1/10 tested) and SETD2 mutation in 1/10 test SCA." (PMID 35267601, 2022). "Hypoxic glioma‐derived EVs harboring upregulated miR‐10b‐5p triggered an M2 phenotype in macrophages as well as enhanced aggressive tumor biology of glioma cells via inhibition of PIK3CA/PI3K/AKT pathway by targeting NEDD4L." (PMID 36052751, 2022). "Our study added to the growing evidence for the activation of PIK3CA in glioma tissues." (PMID 36052751, 2022). "Furthermore, enrichment of PIK3CA mutations in M-GBMs, as well as the effects of PAM inhibitors, which are more selective in patient-derived glioma cells." (PMID 34422657, 2021). "Besides, we also verified with qRT-PCR that PIK3CA mRNA expression was markedly elevated and positively correlated with circ_0000020 expression in glioma tissues and negatively correlated with miR-142-5p expression." (PMID 33509213, 2021). "In this work, it was demonstrated that miR-142-5p could negatively regulate PIK3CA mRNA and protein expressions in glioma cells." (PMID 33509213, 2021). "Circ_0000020 promotes glioma progression via miR-142-5p/PIK3CA axis." (PMID 33509213, 2021).
glioma (continued). "PIK3CA and IDH mutations are an early event in glioma and are associated with progression." (PMID 34374193, 2021). "Importantly, previous studies report that PIK3CA expression is elevated in gliomas and it promotes glioma progression." (PMID 33509213, 2021). "IDHwt GBM PDOXs retained common glioma mutations, including EGFR, MDM4, PTEN, PIK3CA, and PTCH1." (PMID 33009951, 2020). "PIK3CA is an emerging biomarker in glioma as reported by several previous studies." (PMID 33747896, 2020). "Mutations of the PIK3CA gene have been reported in human GBMs and could represent an alternative event to PTEN mutations for deregulating this key, glioma-relevant pathway." (PMID 30818875, 2019). "For instance, a GEMM created to induce a glioma-like tumor with a constitutively active PIK3CA mutant could be used to evaluate whether a new PI3K inhibitor can interfere with downstream signaling of the pathway and cross an intact and/or partially disrupted (mouse) BBB." (PMID 39626263, 2025). "Moreover, research in this field appears significantly outdated—studies exploring the role of PIK3CA mutations considering the most recent glioma molecular stratification are severely lacking." (PMID 40508087, 2025). "In this case, the acquisition of enough samples of each subgroup for a robust analysis might be a challenge, especially as all evidence points to PIK3CA mutations not being too abundant in glioma." (PMID 40508087, 2025). "Thus far, no studies have addressed PIK3CA mutation frequency across the glioma subgroups defined by the 2021 WHO classification." (PMID 40508087, 2025). "Moreover, heparan sulfate-glucosamine 3-sulfotransferase 1 (HS3ST1) and calponin 3 (CNN3) are overexpressed in astrocytoma, and mutations in phosphatidylinositol-4,5-bisphosphate 3-kinase catalytic subunit alpha (PIK3CA), PDGFRA, and MYCN are generally associated with poorer prognosis in gliomas." (PMID 39062515, 2024). "Similarly in cardiac schwannomas, 12/26 (46%) Pik3ca NS variants were described in COSMIC without relevance to central nervous system tumors." (PMID 38232086, 2024). "Therefore, we speculated that NEDD4L could regulate glioma development via PIK3CA and PI3K/AKT pathway." (PMID 36052751, 2022). "Therefore, we speculate that activated PIK3CA drives increased glioma cell migration, resulting in a disseminated malignant phenotype that may escape standard-of-care adjuvant involved-field radiation therapy." (PMID 31036078, 2019). "Copy number was prognostic even for genes in which mutations were not linked with outcome: for instance, while mutations in PIK3CA were never informative, the copy number of PIK3CA was associated with outcome in breast, colorectal, glioma, lung-squamous, pancreas, and prostate cancers." (PMID 30526857, 2018). "In glioma, KAT6A activates phosphatidylinositol-4,5-bisphosphate 3-kinase catalytic subunit alpha (PIK3CA) transcription by recruiting tripartite motif-containing 24 (TRIM24), thereby promoting tumorigenesis." (PMID 40475780, 2025).
glioma (continued). "For example, TRIM24 binds and activates PIK3CA gene engaged oncogenic PI3K/AKT signaling pathway in prostate cancer and glioma." (PMID 28114950, 2017). "PIK3R1 and PIK3CA, genes involved in the PI3K pathway, have been recognized as oncogenes present in grade II–IV gliomas including DIPG." (PMID 28401062, 2017). "We studied the efficacy of DS in 2 intracranial tumor models; the U87 glioma cell line and the GSC11 glioma initiating cell line are both PTEN mutant and GSC-11 is PIK3CA mutant cells." (PMID 28423515, 2017). "Co-occurrence between amplification of EPHB3 and alterations in PIK3CA (both at chromosome 3q26-3q27), and amplifications in PDGFRA, KIT and KDR (all at 4q12) were also found in a subset of RMPAhigh gliomas, due to their localization in the common amplicons." (PMID 27385209, 2016). "All three high grade lines had highly complex genomic profiles and harboured amplifications and deletions at several known cancer genes dysregulated in paediatric glioma, including CCND1, MYC, CDK4, PIK3CA, CDKN2A/B, and RB1." (PMID 19365568, 2009). "Similarly, the genes with increased copy numbers, such as CD4, PIK3CA, and P2RX7, had higher expression levels in glioma, indicating a positive correlation of CNVs with the expression levels of ICD-related genes." (PMID 36428756, 2022). "The clinical characteristics of glioma patients from TCGA consisting of primary therapy outcome, WHO grade, histological type, IDH status, gender, 1p/19q codeletion, age, race, EGFR status, and PIK3CA status were collected." (PMID 34222249, 2021). "Interestingly, mutations in PIK3CA and KRAS were shown to lead to increased aggressiveness in gliomas and tumor progression independent of IDH mutational status." (PMID 40362343, 2025). "Constitutive activation of PI3K pathway by PTEN mutation/loss or PIK3CA mutation could render tumor cells independent of RTKs for malignant transformation and maintenance, which leads to resistance to HER2-targeted therapies in BC and EGFR-targeted therapies in glioma." (PMID 27484095, 2016).